CST3 (cystatin C)
Diseases named in the same sentence as CST3 in open-access papers (continued):
Sharing a sentence is not in itself a finding about the gene and the disease.
sarcopenia (continued). "Taking into account the current diagnostic criteria for sarcopenia, these findings further support the utility of the creatinine/cystatin C ratio as a marker of sarcopenia." (PMID 34836249, 2021). "In fact, several studies have shown the close association of the creatinine/cystatin C ratio with the diagnosis of sarcopenia according to contemporary guidelines." (PMID 34836249, 2021). "The aim of this study was to evaluate the diagnostic value of the sarcopenia index (serum creatinine [mg/dl]/cystatin C [mg/dl] × 100) for estimating low muscle mass and sarcopenia in community-dwelling older adults." (PMID 30068907, 2018). "AD was significantly related to central fat, metabolic syndrome, sedentarity and skeletal sarcopenia, as well as to hsCRP, fibrinogen, uric acid, cystatin-C, Big ET-1, and 10-year UKPDS CV risk." (PMID 23046637, 2012). "Cystatin C may reflect renal function decline, and renal dysfunction is associated with sarcopenia and cardiovascular events." (PMID 40537082, 2025). "Notably, evidence demonstrates that a reduced serum creatinine-to-cystatin C ratio (Cr/cysC) exhibits independent associations with both sarcopenia prevalence and elevated atherosclerotic plaque burden in type 2 diabetes populations." (PMID 40756518, 2025). "Furthermore, a recent cross-sectional analysis showed that estimation of eGFR by use of CKD-EPIBTP-B2M was independently associated with sarcopenia in community-dwelling older individuals in contrast to creatinine and cystatin C-based equations." (PMID 39055699, 2024). "Because patients with sarcopenia may have a falsely low SCr and obesity is associated with elevated cystatin C, we hypothesized that CT‐defined sarcopenia and high adiposity will each be associated with a large discordance between eGFRCRE and eGFRCYS." (PMID 38646842, 2024). "Serum creatinine (Cr)- and cystatin C (CysC)-based indices have been suggested as alternative markers for sarcopenia, but their predictive value for sarcopenia risk is uncertain, which was investigated in the present study in the Chinese population with the middle and older ages." (PMID 39634549, 2024). "And systemic immune inflammation (SII), platelet‐to‐lymphocyte ratio (PLR), modified geriatric nutritional risk index (mGNRI), creatinine and sarcopenia index (SI, (creatinine/cystatin C) × 100) were determined as independent predictors (p < 0.05) in multivariate Cox proportional hazards regression." (PMID 39449162, 2024). "Because cancer is an important risk factor for sarcopenia and frailty, we hypothesized that having a cystatin C–based eGFR (eGFRcys) that is substantially lower than an eGFRcr would be common in patients with cancer." (PMID 37405775, 2023). "Recent studies suggest that serum creatinine-cystatin C (Cr/CysC) ratio may be associated with sarcopenia, but this association lacks sufficient evidence in patients with gastrointestinal stromal tumours (GIST)." (PMID 36118766, 2022). "In addition, abnormal values of some serum/plasma parameters were suggested as possible markers of muscle loss and possibly sarcopenia, such as the creatinine to cystatin C ratio, irisin, sclerostin, and brain natriuretic peptide." (PMID 35565832, 2022). "To demonstrate the association of the serum creatinine/serum cystatin C ratio (sarcopenia index, SI) with clinical outcomes including cardiovascular and bleeding risk in older patients who underwent percutaneous coronary intervention (PCI), we analyzed a multicenter nation-wide pooled registry." (PMID 32992530, 2020). "To investigate the association of the sarcopenia index (SI, serum creatinine value/cystatin C value × 100) with 3-year mortality and readmission among older inpatients, we reanalyzed a prospective study in the geriatric ward of a teaching hospital in western China." (PMID 31988356, 2020). "The sarcopenia index (SI), which combines cystatin C with the estimated glomerular filtration rate, has also been studied." (PMID 41598223, 2026).
sarcopenia (continued). "We identified seven robust protein signatures (LRG1, CST3, TIMP1, C2, ITIH1, AMBP and LYZ) that showed consistent significant associations with sarcopenia components in both cohorts." (PMID 41782349, 2026). "The creatinine-to-cystatin C ratio (CCR) has been developed as a novel biomarker of sarcopenia and prognostic evaluation in various hospitalized populations." (PMID 41340661, 2025). "Several studies have shown that the Cystatin C‐Creatinine ratio serves as an effective biomarker for muscle mass and sarcopenia, reflecting overall health deterioration in ageing populations." (PMID 40817389, 2025). "Conversely, the combination of cystatin-c and creatinine exhibits poor efficiency in diagnosing muscle wasting and sarcopenia phenotype in community dweller geriatric population." (PMID 40095091, 2025). "The serum creatinine-to-cystatin C ratio, also known as the sarcopenia index (SI), has recently emerged as a promising biomarker for assessing muscle mass and function." (PMID 41465771, 2025). "If feasible, we recommend considering the use of extended kidney function biomarkers such as cystatin-C and inulin or iohexol clearance to better assess kidney function in oncologic settings with possible secondary sarcopenia." (PMID 40493263, 2025). "The SI was defined as 100 × creatinine / cystatin C. Diagnosis of sarcopenia based on the Asian Working Group for Sarcopenia 2019 consensus." (PMID 39623162, 2025). "Serum indices based on creatinine (Cr) and cystatin C (CysC) have been proposed as potential biomarkers for development and progression of sarcopenia." (PMID 40852370, 2025). "The serum creatinine-to-cystatin C ratio (sarcopenia index, SI) has emerged as a cost-effective biomarker of muscle mass and function, while physical activity (PA) is a key protective factor." (PMID 41465771, 2025). "The sarcopenia index (SI), derived from serum creatinine and cystatin C levels, has emerged as a novel and accessible biomarker for predicting clinical outcomes." (PMID 40046757, 2025). "The serum creatinine/serum cystatin C ratio, called the sarcopenia index (SI), is used as a surrogate marker for sarcopenia." (PMID 41303064, 2025). "Previous studies have used a combination of plasma cystatin-c and creatinine levels for diagnosing sarcopenia." (PMID 40095091, 2025). "The creatinine-to-cystatin C ratio (CCR) has recently been proposed as a proxy indicator for sarcopenia." (PMID 40502396, 2025). "Several biomarkers have been identified for sarcopenia, including the creatinine/cystatin C ratio, C-terminal agrin fragment, and multiple microRNAs (miR-7a-1-3p, miR-135a-5p, miR-151-5p, miR-196b-5p)." (PMID 40076542, 2025). "Both sarcopenia indices (traditional and new SI) are derived from serum creatinine and cystatin C values, which are commonly measured in patients with CKD and recognized for reflecting sarcopenia and other diseases." (PMID 39795624, 2025). "Despite the improvements afforded by the CKD-EPI cystatin C equation, we recognize that eGFR remains a complex predictor of sarcopenia." (PMID 41262446, 2025). "In a meta-analysis, using the ratio of creatinine to cystatin C for the diagnosis of sarcopenia, the sensitivity, specificity, and AUC were 65%, 79%, and 0.78, respectively." (PMID 39623162, 2025). "This prospective observational study investigated the utility of serum indices based on creatinine and cystatin C to screen for low muscle mass, a key component of sarcopenia, in patients with MASLD." (PMID 40852370, 2025). "The serum creatinine/serum cystatin C ratio (Scr/Cys C ratio) has recently been recognized as a valuable indicator for assessing sarcopenia." (PMID 38965150, 2024). "Previous studies have shown that Creatinine/Cystatin C (CCR) is a substitute indicator for sarcopenia in patients with gastric cancer, gastrointestinal stromal tumors, and esophageal cancer." (PMID 38706605, 2024).
sarcopenia (continued). "The primary advantage is our thorough evaluation of the impact of serum Cr- and cystatin C-based measures on subsequent sarcopenia among middle-aged and older Chinese adults in a nationally representative retrospective cohort study." (PMID 39634549, 2024). "Many studies have underscored the robust relationship between sarcopenia and various biomarkers, such as the serum creatinine/cystatin C ratio, γ-glutamyltransferase, HOMA-IR index, etc., elucidating the intricate mechanisms underlying the condition." (PMID 39224122, 2024). "In another study, a lower CCR and a lower SI (sarcopenia index, SI = serum creatinine × cystatin C) are independent predictors of mortality, in metastatic non-small cell lung cancer patients treated with PD-1 inhibitors." (PMID 38776028, 2024). "Multiple screening tools that incorporate serum creatinine (Cr) and cystatin C (CysC) levels have been proposed as alternative biological markers for diagnosing sarcopenia." (PMID 39634549, 2024). "On the other hand, there are many reports on the associations of cystatin-C-related indices, including the creatinine-to-cystatin-C ratio (Cre/CysC ratio) and estimated glomerular filtration rate based on CysC (eGFRcys), with physical frailty and sarcopenia." (PMID 39796450, 2024). "validated the correlation between the creatinine‐to‐cystatin C ratio and muscle mass and defined it as a sarcopenia index in 2017." (PMID 39449162, 2024). "The serum Cr-to-cystatin-C ratio (CCR) is the first available index for sarcopenia by estimating the muscle mass and acting as an independent predictor of hospitalization and the 90-day mortality in ICU patients." (PMID 39634549, 2024). "Future studies on sarcopenia in patients with CKD will need to use cystatin C to accurately estimate kidney function." (PMID 37222019, 2023). "first developed the creatinine/cystatin C ratio and verified the correlation between creatinine/cystatin C ratio and sarcopenia." (PMID 37409249, 2023). "It has been suggested that cystatin C can be used as an alternative endogenous marker to evaluate renal function in patients having or likely to have sarcopenia because it is unaffected by muscle mass." (PMID 37959364, 2023). "Since HRI is expected to be directly related to sarcopenia by principle, we attempted to use CC as a screening test and established cutoff values for ordering a cystatin C test in elderly patients." (PMID 37959364, 2023). "Recent reports have suggested that the creatinine/cystatin C ratio in peripheral blood can be used to predict sarcopenia and prognosis in patients with cancer." (PMID 37409249, 2023). "Recently, the sarcopenia index (SI; serum creatinine [Cr, mg/dL]/cystatin C [CysC, mg/L] × 100) has been recommended as a novel screening tool for sarcopenia." (PMID 36774462, 2023). "For simple screening, the OFI-8 can be used for oral frailty and cystatin C-related indices such as Cr/CysC and eGFRcys/eGFRcre for physical frailty/sarcopenia; the present study shows that they are significantly associated with each other." (PMID 37093792, 2023). "Secondly, this study lacks data to evaluate sarcopenias, such as CT, DXA, and BIA, which further restricts the explanation of the association between creatinine/cystatin C ratio and muscle mass." (PMID 37409249, 2023). "Conventionally, cystatin C-related indices have been considered effective in screening systemic frailty and sarcopenia, whereas the OFI-8 index is considered effective in screening oral frailty." (PMID 37093792, 2023). "The SI quantifies sarcopenia by finding the ratio of creatinine to cystatin C serum levels, both markers of glomerular filtration rate (GFR)." (PMID 37038595, 2023). "The sarcopenia index (SI, serum creatinine/serum cystatin C × 100) is recommended for predicting sarcopenia." (PMID 37026117, 2023). "Recently, the sarcopenia index (SI) was developed as a surrogate marker of sarcopenia based upon the serum creatinine to cystatin C ratio." (PMID 36774462, 2023).
sarcopenia (continued). "Multivariable logistic regression analysis for ability of creatinine to cystatin-C ratio (below median of 1.0) to predict sarcopenia utilizing Emory and Martin sarcopenia cutoffs." (PMID 37540787, 2023). "Several recent studies have shown that the ratio of creatinine to cystatin C can be used as an indicator of both muscle mass and muscle function and, therefore, the Creatinine/CystatinC (Cr/CysC)*100 was proposed as a sarcopenia index (SI)." (PMID 37841730, 2023). "Lower serum creatinine and cystatin C ratio is related to lower skeletal muscle mass and the higher likelihood of sarcopenia." (PMID 36158553, 2022). "We aimed to employ the simple and economic indicator sarcopenia index (SI = creatinine/cystatin C ×100) to screen for sarcopenia and to evaluate its prognostic value in patients with esophageal cancer (EC)." (PMID 35287579, 2022). "In this study, the association between renal function and NF-L is based on cyctatin C. Cystatin C was initially chosen because creatinine is known to be influenced by muscle mass and this cohort was initially designed to evaluate prevalence of sarcopenia." (PMID 35018623, 2022). "Expanding the use of Creatinine/Cystatin C would allow for early and targeted treatment of sarcopenia." (PMID 36017221, 2022). "Low CC (<31.5 cm for males, <29.6 cm for females) would be an alternative parameter to indicate cystatin C preference for possible sarcopenia." (PMID 36530922, 2022). "Previous studies on markers of sarcopenia have mostly focused on serum creatinine and cystatin C, but also on related inflammatory mediators such as C-reactive protein (CRP), tumor necrosis factor-alpha (TNF-α), and interleukins (IL)." (PMID 36046129, 2022). "In patients with COPD, the serum cystatin C levels were reported to be higher in the sarcopenia group than that in the robust group; however, the serum Cr/CysC ratio was significantly more useful than the serum cystatin C level." (PMID 35606777, 2022). "The product of serum creatinine and the estimated glomerular filtration rate based on cystatin C (Cr×eGFRcys) was recently proposed as a sarcopenia index (SI), approximately to 24-h filtered creatinine through the glomerulus." (PMID 35284461, 2022). "The creatinine/cystatin C ratio or creatinine/cystatin C × 100 was an indicator to sarcopenia index (SI) for the prediction of liver injury and sarcopenia in liver disease and monitoring the progression of non-alcoholic fatty liver disease." (PMID 36466932, 2022). "The sarcopenia index (SI, serum creatinine/serum cystatin C × 100) is recently suggested to be a reliable marker for sarcopenia." (PMID 36158553, 2022). "Spearman's correlations between different proposed sarcopenia indices based on creatinine and cystatin C with skeletal muscle mass, strength, and gait speed." (PMID 35284461, 2022). "Urea-to-creatinine ratio and the creatinine-to-cystatin C ratio (known as the sarcopenia index) are both potential biomarkers of catabolism, as they were correlated to muscle mass." (PMID 35268097, 2022). "The ratio of creatinine to cystatin C (Cre/CysC), a marker of muscle function and muscle mass, can be used to predict sarcopenia in different populations." (PMID 36337638, 2022). "Recently, a surrogate marker for sarcopenia called sarcopenia index (SI) has deen developed, which is defined as serum creatinine (mg/dL)/cystatin C (mg/L) × 100 and can be used to evaluate the skeletal muscle mass." (PMID 36158553, 2022). "The use of the creatinine to cystatin C ratio as a sign of low muscle mass was first proposed by Tetsuka, later called the sarcopenia index and validated among critically ill patients in intensive care units." (PMID 34836249, 2021). "Recently, the creatinine/cystatin C ratio and CONtrolling NUTritional status score were introduced as biochemical indicators for sarcopenia and malnutrition, respectively." (PMID 34413410, 2021).
sarcopenia (continued). "In recent years, the sarcopenia index (SI, serum creatinine [mg/dl]/cystatin C [mg/l] × 100) has been recommended to evaluate skeletal muscle mass." (PMID 34641805, 2021). "All four sarcopenia indices based on serum creatinine and cystatin C, which are simple and widely available in the clinical setting, predicted overall mortality independently of well-established risk factors in patients with non-dialysis CKD." (PMID 34413438, 2021). "Serum indices based on creatinine and cystatin C, two commonly used indicators of renal function, are recently identified as serum markers for sarcopenia." (PMID 34413438, 2021). "By contrast, an indicator that can be easily calculated that reflects skeletal muscle simply is the serum creatinine/serum cystatin C ratio, the so-called sarcopenia index (SI)." (PMID 32992530, 2020). "Cystatin-C based eGFR is recommended to trace the renal function in these patients, especially in male patients with cirrhosis and sarcopenia." (PMID 32287280, 2020). "The sarcopenia index based on serum creatinine and cystatin C cannot accurately detect either low muscle mass or sarcopenia in urban community-dwelling older people with normal kidney function when using four common criteria as the “gold standards”." (PMID 30068907, 2018). "Creatinine‐based estimated eGFR may overestimate kidney function in patients with sarcopenia, whereas cystatin C‐based eGFR is less influenced by muscle mass." (PMID 41457350, 2026). "The creatinine-to-cystatin C ratio (CCR), a surrogate for skeletal muscle mass, may also be associated with liver fibrosis due to the strong link between sarcopenia and liver disease progression." (PMID 41096824, 2025). "Although sarcopenia pathophysiology is increasingly understood, prior studies on the SI in HF have employed uniform sex thresholds, neglecting sex-specific variations in creatinine-cystatin C dynamics critical for prognostic accuracy." (PMID 40046757, 2025). "In this longitudinal study with the middle and older age of population (aged ≥45 years) in China, we found that among the four indices based on serum Cr and cystatin C, only the decrease in pSMI and TBMM was associated with an increased risk of the subsequent development of sarcopenia." (PMID 39634549, 2024). "For series 1, the group agreed on 4 biochemical markers that should be assessed in Phase II or Phase III trials (i.e., Myostatin-Follistatin, Brain Derived Neurotrophic Factor, N-terminal Type III Procollagen and Serum Creatinine to Serum Cystatin C Ratio – or the Sarcopenia Index)." (PMID 36633611, 2023). "One candidate that may assist in the detection of sarcopenia is the creatinine (Cr) to cystatin-C (Cys-C) ratio (Cr/Cys-C)." (PMID 37540787, 2023). "The use of creatinine in sarcopenia patients with reduced muscle mass or muscle wasting may overestimate kidney function and further studies using cystatin C will be required to accurately assess kidney function in patients with CKD." (PMID 37222019, 2023). "People with higher cystatin C and lower hemoglobin were more commonly found to have sarcopenia." (PMID 36992883, 2023). "The study hypothesis is that CCR (creatinine/cystatin C ratio), or the SI (sarcopenia index) may predict sarcopenia, falls, and further fractures in a population with a high fragility fracture risk." (PMID 36501049, 2022). "Because creatinine and cystatin C have unique metabolic processes, the ratio of these two substances may more accurately reflect muscle mass and sarcopenia, and some scholars refer to this as the sarcopenia index (SI)." (PMID 39623162, 2025). "Therefore, it may be imperative to investigate other biomarkers in combination with cystatin-c to predict the future onset of sarcopenia." (PMID 40095091, 2025). "Consequently, the ratio of creatinine to cystatin C (i.e., the sarcopenia index) might have higher predictive efficiency." (PMID 39449162, 2024).